INSR (insulin receptor)
Diseases named in the same sentence as INSR in open-access papers (continued):
Sharing a sentence is not in itself a finding about the gene and the disease.
Insulin resistance (continued). "Upon initiating the inflammatory cascade, activating serine kinases, such as JNK and IKK, can lead to serine phosphorylation of the insulin receptor substrate (IRS), leading to insulin signaling inhibition and cellular insulin resistance." (PMID 39328924, 2024). "Changes in S1P levels in obese and diabetic individuals can result in abnormalities in downstream insulin receptor signaling pathways, such as PI3K/Akt, thus impacting insulin sensitivity and fostering the development of insulin resistance." (PMID 39777222, 2024). "Given the importance of InsR recycling in the development of insulin resistance, understanding the role of PI3K in regulating InsR expression on the PM is critical." (PMID 37693391, 2024). "The final product of its transcription in the cell nucleus will produce more proinflammatory cytokines, ultimately inhibiting tyrosine phosphorylation of the insulin receptor substrate (IRS), thereby increasing insulin resistance." (PMID 39519516, 2024). "In the context of insulin resistance, IL-6 interferes with insulin signaling pathways by activating serine kinases, such as c-Jun N-terminal kinase (JNK), which phosphorylate insulin receptor substrate proteins and disrupt insulin receptor signaling." (PMID 38044678, 2024). "Metformin improves insulin resistance by increasing the recruitment and activity of the glucose transporter GLUT4 as well as improving tyrosine kinase (insulin receptor) activity." (PMID 39518747, 2024). "Elevated NCOR2 levels increase insulin (INS) production, which subsequently decreases INSR expression and AKT phosphorylation (p-AKT), leading to the development of insulin resistance and ultimately hyperglycemia." (PMID 39337631, 2024). "S1-promoted GRB14, which is a negative regulator of the insulin receptor (INSR), represses post-receptor insulin signaling and increases insulin resistance." (PMID 38674024, 2024). "Insulin signaling is thus suppressed downstream of the insulin receptor (IR) at the level of IR substrate-1 (IRS-1) and PI3K, which together promote insulin resistance in peripheral tissues." (PMID 38255314, 2024). "These structures have been shown to play a role in insulin receptor-mediated signaling and GLUT4 trafficking in skeletal muscle, with impaired function potentially leading to insulin resistance." (PMID 39085321, 2024). "Obesity is a major factor responsible for insulin resistance and leads to T2DM; because of insulin receptor (IR), three crucial insulin-responsive tissues such as the liver, skeletal muscle, and adipose tissues become insulin insensitive." (PMID 39759127, 2024). "Methylation of PRKCZ in the underfed group negatively correlated with INSR and IRS1 expression, and positively with CRP, showing a relationship between methylation and inflammatory and insulin resistance markers." (PMID 38256201, 2024). "The present study evaluated the effect of insulin, an insulin receptor antagonist, and a TLR4 inhibitor on behavioral deficits and insulin resistance induced by 6-hydroxydopamine (6-OHDA)." (PMID 39830652, 2024). "These downstream effectors can mediate insulin resistance directly by downregulating GLUT4 and insulin receptor expression, promoting serine phosphorylation of insulin receptor substrate (IRS-1), or indirectly by inducing inflammatory factors and ROS51." (PMID 38704482, 2024). "Studies have shown that BBR primarily improves glycemic control and reduces insulin resistance through various mechanisms, such as activating AMPK, upregulating insulin receptor (InsR) expression, regulating gut microbiota, and promoting GLP-1 secretion." (PMID 39640489, 2024). "One of the hallmarks of insulin resistance is increased phosphorylation of IRS1 protein at Ser307, which inhibits the insulin receptor signaling cascade." (PMID 39268230, 2024). "Variants within this cluster mapped to genes with known effects on insulin resistance, including IGF2, INSR, KLF14, and PPARG in adipose tissue." (PMID 38200577, 2024).
Insulin resistance (continued). "The expression levels of INSR, IRS-1 and p-IRS-1 in the liver and skeletal muscle of HF group mice decrease gradually with the progress of insulin resistance, while those in the ovary organ present the opposite trend." (PMID 37830511, 2023). "FFAs are other factors involved in the induction of hepatic insulin resistance via several mechanisms, including PKC-δ, phosphorylation of Akt, IRS-1, insulin receptor, and de novo lipogenesis." (PMID 37876013, 2023). "In this research, we looked into the impacts of PSC-FEs on two principal pathways involved in insulin resistance, i.e., AMPK and AKT and also on expression levels of INSR, GLUT1, and GLUT4, as major regulators of glucose hemostasis." (PMID 37158952, 2023). "The insulin receptor INSR is one of the downstream target genes of FoxO1 and is upregulated through PERK activation, inducing cellular insulin resistance." (PMID 36830968, 2023). "Several genes are alternatively spliced in insulin resistance and T2DM; notably, the insulin receptor gene itself is alternatively spliced and regulated by its own hormone ligand, insulin." (PMID 37762628, 2023). "Knockdown of METTL4 led to downregulation and inactivation of the INSR pathway, thereby regulating the IRS-1/PI3K/AKT pathway to improve insulin resistance." (PMID 37998047, 2023). "In addition to the adaptive increase of blood adiponectin level, insulin resistance or compromised insulin receptor signaling pathway may downregulate expression of insulin degrading enzyme (IDE), a downstream target of the pathway and protease that digests Aβ as well as insulin." (PMID 37191420, 2023). "For instance, Diacylglycerol induces insulin resistance through activation of Protein kinase C epsilon type enzyme (PKC-ε) and decreased insulin receptor (IRS-2) tyrosine phosphorylation." (PMID 37759824, 2023). "Mulberry polysaccharide can upregulate the expression of the insulin receptor InsR, insulin substrate receptor IRS-2, and glucose transporter in type II diabetic rats and lower insulin resistance." (PMID 36765969, 2023). "In hepatocytes experiencing insulin resistance, the regulation of insulin signal transduction becomes compromised, and the PI3K/Akt signaling pathway, downstream of the insulin receptor, is suppressed." (PMID 37759297, 2023). "The authors reported a decreased expression in insulin receptor (IR-β) and insulin receptor substrate (IRS-1), leading to insulin resistance." (PMID 36077184, 2022). "At the molecular level, dysregulation of the insulin receptor (IR) and insulin receptor substrate (IRS) proteins is a common feature of insulin resistance." (PMID 35682723, 2022). "CYP2J3 overexpression in db/db mice improved insulin resistance, decreased endoplasmic reticulum stress by activating the AMPK and insulin receptor (IR)-PI3K-AKT signaling pathway." (PMID 35744996, 2022). "An independent risk factor for type 2 diabetes is the plasma levels of AHSG, which is an insulin receptor inhibitor secreted by the liver and, along with FETUB, thought to be an important factor in insulin resistance in obesity." (PMID 35745003, 2022). "Most obese phenotypes are accompanied by the inhibition of insulin receptor substrate and AKT and increased insulin resistance." (PMID 35565942, 2022). "In mechanism, MG53, as an E3 ligase, performs ubiquitin-dependent degradation of insulin receptor (IR) and insulin receptor substrate (IRS1), leading to insulin resistance and metabolic disorders." (PMID 36479346, 2022). "Increased TNF-α levels affect the insulin receptor substrate (IRS) proteins, leading to insulin resistance." (PMID 36230942, 2022). "By binding to the Toll-like receptor-4 (TLR-4)–CD14 complex, Lipopolysaccharide (LPS) activates the immune system, interfering with the insulin receptor and leading to an increase in testosterone production resulting in PCOS and insulin resistance." (PMID 34357331, 2021).
Insulin resistance (continued). "IL-1α and IL-1β have been reported to impair insulin signaling by altering tyrosine phosphorylation of insulin receptor substrate (IRS-1 and IRS-2), which leads to insulin resistance." (PMID 33924165, 2021). "DGs can induce insulin resistance in skeletal muscle by activating PCK-Θ, impairing the insulin receptor substrates’ ability to activate PI3 kinase." (PMID 34436382, 2021). "On the other hand, in adipose tissue and liver, IL-6 exerts proinflammatory activities and induces insulin resistance by upregulating suppressor of cytokine signalling 3 (SOCS3), which is a protein that binds to and inhibits insulin receptor." (PMID 33800490, 2021). "JNK1-mediated disruption of insulin receptor/insulin receptor substrate 1 (IRS1) interaction and the resulting insulin resistance are dependent on IRS1 phosphorylation at both Ser302 and Ser307." (PMID 34959870, 2021). "In the cultured human hepatocytes, Berberine increases Insulin receptor (InsR) mRNA and also activates AMPK in adipocytes, which has been shown to reduce insulin resistance." (PMID 34094026, 2021). "In another report, it was found that the infusion of ADSCs alleviated hyperglycemia and insulin resistance in T2DM rats via restoration of glucose transporter-4 (GLUT4) and INSR expression on the cell membrane of the skeletal muscle, liver, and adipose tissue." (PMID 33957965, 2021). "Animal data suggest that IL-6 mediates hepatic insulin resistance via SOCS3, which blocks autophosphorylation of the insulin receptor." (PMID 34747368, 2021). "Based on the pathway enrichment analysis, targets (INSR, PTPN1, PPARA, PPARG) from two of the most significant pathways, Insulin resistance, and PPAR signaling pathway, were selected for further experimental validation." (PMID 34579756, 2021). "In the validation of pathways, key targets (INSR, PTPN1, PPARA, and PPARG) from two of the most significant pathways in pathway enrichment analysis, Insulin resistance, and PPAR signaling pathway, were selected." (PMID 34579756, 2021). "That is to say, insulin acts on insulin receptor to activate PI3K/Akt pathway, and then the expression of ANGPTL8 increases; in insulin resistance, PI3K/Akt pathway was damaged and ANGPTL8 expression was downregulated." (PMID 34582711, 2021). "In particular, since the binding of insulin to the insulin receptor (IR) leads to the activation of PI3K/AKT and inactivation of GSK3-β, any disturbance in this transduction pathway will result in insulin resistance." (PMID 34830036, 2021). "In 3T3-L1 adipocytes, however, activation of MAPKs including ERK, JNK, and P38 has been shown to reduce tyrosine phosphorylation of insulin receptor and IRS, decrease glucose transporter GLUT4, and induce insulin resistance." (PMID 33647469, 2021). "Increased ROS production results in the inhibition of insulin receptor autophosphorylation and inhibition of IRS-1 protein phosphorylation, which promotes insulin resistance." (PMID 32823917, 2020). "However, there are several genetic syndromes of severe insulin resistance that have illuminated our understanding of the basic biology of insulin signaling and resistance, for example, the autosomal recessive insulin receptor (INSR) defects seen in Donohue syndrome and Rabson-Mendenhall syndromes." (PMID 33210059, 2020). "Since the liver is one of the primary target organs of insulin action, levels of key proteins involved in insulin signaling pathway including InsR, IRS2, and phospho-Akt were detected to investigate insulin resistance in all experimental groups." (PMID 32132984, 2020). "So far, multiple studies have demonstrated the ability of metformin to activate the hepatic insulin receptor and the IRS2/PI3K/Akt pathway resulting in reduced insulin resistance and increased glucose uptake." (PMID 32780768, 2020).
Insulin resistance (continued). "The mice in the HLU and HLS groups did not exhibit insulin resistance associated with hyperinsulinemia, suggesting that the antioxidant/anti-inflammatory effect of HDLc and phenolic compounds present in grape juice prevented the oxidation of insulin receptor substrates." (PMID 32881885, 2020). "This genotype-phenotype study provides clues that THADA, INSR, TOX3, and DENND1A play important role in the etiology of PCOS, possibly through insulin resistance and metabolic disorder related pathways." (PMID 32425888, 2020). "Insulin promotes glucose uptake through a series of signaling events triggered by binding to the insulin receptor and activating IRS1 phosphorylation, and IRS1-PI3K signaling is suppressed during insulin resistance." (PMID 33292347, 2020). "ER stress induces insulin receptor signaling through increasing the serine phosphorylation and decreasing the tyrosine phosphorylation of IRS-1 (IRSpY), leading to insulin resistance." (PMID 32180905, 2020). "Recent research of insulin receptor signaling indicates that the accumulation of FFA in muscle can interfere with insulin signaling and produce insulin resistance." (PMID 32178449, 2020). "As a result, aged Cdk1 cKO mice develop hepatic insulin resistance, likely through reduced INSRB expression and reduced insulin receptor auto-phosphorylation." (PMID 33345777, 2020). "By inhibiting insulin-stimulated tyrosine phosphorylation of insulin receptor and insulin receptor substrate-1, TNF-α can play a crucial role in systemic insulin resistance and also decipher a clear link between obesity, insulin resistance and T2D." (PMID 32188105, 2020). "This is in agreement with previously reported data, which indicated that obesity-induced inflammation, repress insulin receptor signaling (IRS), and contribute to insulin resistance development." (PMID 32899471, 2020). "It has been shown that TNF-α contributes to insulin resistance through impairment of insulin signaling by increasing serine phosphorylation of insulin receptor substrate- (IRS-) 1 and diminishing insulin receptor (IR) tyrosine kinase activity." (PMID 31828161, 2019). "In some insulin-resistant patients, protein tyrosine phosphatase 1B (PTP1B) interacted with insulin receptor and induced insulin receptor dephosphorylation, resulting in inactivation of insulin signaling pathway." (PMID 31396083, 2019). "Activation of protein kinase C and subsequent inactivation of insulin receptor attenuate insulin-stimulated insulin receptor substrate 1 and 2 (IRS 1/2) tyrosine phosphorylation, a well-studied mechanism for accelerated hepatic insulin resistance." (PMID 30717198, 2019). "It has been extensively reviewed for INSR downstream signaling pathways such as PI3-kinase (PI3K)/AKT and Ras/Raf/MEK/ERK and their alterations under insulin resistance state." (PMID 31658625, 2019). "The molecular impact of the insulin receptor present within these cell types of the BBB is gaining great interest, likely due to the link in CNS insulin resistance and Alzheimer’s disease." (PMID 31213970, 2019). "Molecular basis of oxidative stress-induced insulin resistance has been attributed to ROS triggering the activation of serine/threonine kinase cascades (NF-κB, JNK, MAPK) which phosphorylate insulin receptor and insulin receptor substrate." (PMID 31467574, 2019). "Brain-specific insulin receptor (IR)-knockout (NIRKO) mice are an animal model of both obesity and insulin resistance." (PMID 30875909, 2019). "This discrepancy may be explained by the biological differences between INSR-deficient mice, which is a suitable model for insulin deficiency taking place in long-standing T2D and obese subjects who exhibited insulin resistance phenotype but no manifest diabetes." (PMID 31749085, 2019). "To assess the molecular basis of insulin resistance observed in HFD-ΔdblGATA mice, we investigated insulin receptor signalling after infusion of insulin through the portal vein." (PMID 29967467, 2018).
Insulin resistance (continued). "Berberine can decrease insulin resistance by activating PKC, and inhibitor of PKC can eliminates InsR activation and InsR mRNA transcription induced by berberine." (PMID 29930696, 2018). "This concept was impressive demonstrated in the liver specific insulin receptor KO (LIRKO) mice, as a genetic model of isolated hepatic insulin resistance." (PMID 29587401, 2018). "Cardiac-specific overexpression of this molecule leads to proteasomal degradation of both insulin receptor and IRS-1 resulting in insulin resistance." (PMID 30425649, 2018). "As Lin28a directly promotes HMGA1 translation, it has been postulated that in muscle-specific Lin28a knockout mice, insulin resistance is, at least in part, due to reduced HMGA1 levels and consequently impaired INSR expression." (PMID 30034366, 2018). "InsR and IRS1 are the key proteins of the insulin signal pathway, and inhibition of mouse InsR and IRS1 activity can lead to insulin resistance in mice." (PMID 28432282, 2017). "Insulin stimulates tyrosine phosphorylation of insulin receptor signalling (IRS) proteins, which is a crucial event in mediating insulin action and is the primary signalling defect of systemic insulin resistance." (PMID 28435687, 2017). "In accordance with INSR and IRS-1, AKT phosphorylation was significantly reduced (P<0.05) in WT FF-fed mice, co-substantiating insulin resistance." (PMID 28406477, 2017). "At the same time, IKK is the serine kinase of insulin receptor and IRS-1, which can active the phosphorylation of IRS1-Ser307, and result in insulin resistance." (PMID 29240812, 2017). "INSR has an important role in insulin metabolism, consistent with a very common explanation for the pathogenesis of PCOS, namely, insulin resistance." (PMID 27217259, 2016). "The development of insulin resistance and impairment of glucose tolerance in mice treated with BPA finds an explanation in the deregulation of insulin receptor pathway in mice skeletal muscles and livers." (PMID 27782064, 2016). "The majority of patients present with severe hyperglycemia and extreme insulin resistance because of the insulin receptor-antagonizing action of the autoantibodies, but some patients may present with hypoglycemia due to agonist activity of anti-insulin receptor antibodies." (PMID 27142369, 2016). "The insulin resistance subphenotype of SHORT syndrome patients, who have a functional defect lying between INSR and AKT2 in the insulin signaling pathway, closely resembles that seen in INSR dysfunction." (PMID 27766312, 2016). "TNF attenuates the insulin-stimulated tyrosine phosphorylation of insulin receptor (IR) and insulin receptor substrate 1 (IRS1) in adipose tissue and muscle, resulting in the occurrence of insulin resistance." (PMID 28025491, 2016). "In summary, in vivo, ex vivo, and in vitro studies demonstrate that BPA exposure induces decreased adiponectin production by adipose cells and deregulates insulin receptor signaling and GLUT4 expression in muscles and livers, inducing insulin resistance." (PMID 27782064, 2016). "Klotho inhibits signals of insulin/IGF-1 receptors (IR/IGF-Rs), and insulin receptor substrate 1 (IRS1), and induces insulin resistance." (PMID 27861640, 2016). "In the present study, HFD-induced LAR expression in parallel with insulin resistance in the liver, while silencing of LAR expression in liver of HFD mice restored phosphorylation of insulin receptor." (PMID 28044141, 2016). "Protein tyrosine phosphatase 1B (PTP1B), which can directly dephosphorylate both the insulin receptor and insulin receptor substrate 1 (IRS-1), thereby terminating insulin signaling, reportedly plays an important role in insulin resistance." (PMID 26402673, 2015). "For example, Grimble proposes in a review in 2002 over inflammatory status and insulin resistance that TNF-α, via reduced phosphorylation of a subunit of the insulin receptor, contribute to development of insulin resistance." (PMID 26457080, 2015).